CD44 (CD44 molecule (IN blood group))
Diseases named in the same sentence as CD44 in open-access papers (continued):
Sharing a sentence is not in itself a finding about the gene and the disease.
tumor (continued). "The crosstalk between HA and CD44 regulates a number of biological processes leading to tumor cell stemness, invasion, and metastasis." (PMID 36226253, 2022). "When matching normal vs tumor tissues among each marker, only CD44 was dominantly expressed in patients from urban areas, regardless of the type of tissue, while the expression of CD166 and CD133 followed the pattern of a mirror image." (PMID 36291969, 2022). "Ectopic expression of miR-34a in bulk PCa cells or purified CD44+ cells exerted significant antitumor effects on tumor growth and metastasis in vivo." (PMID 36139695, 2022). "Here, we utilized a bioinformatics analysis and identified overexpression of KRAS/MMP7/CD44 oncogenic signatures in CRC tumor tissues compared to normal tissues." (PMID 35203586, 2022). "Drug resistant cells exhibit increased incidence in stem cell specific tumor spheroid formation, upregulated expressions of cell surface markers CD44 and CD133, and nuclear transcription factor c-Myc in vitro." (PMID 35269660, 2022). "In contrast, the CD44 Mes marker is poorly expressed in the periphery but is enriched in the innermost region of the tumor." (PMID 35205179, 2022). "This study showed the inhibition of cell proliferation and tumor-sphere formation in 3D cultures upon CD44 inactivation." (PMID 35785191, 2022). "In nanodiamond-treated animals, the overwhelming presence of CD44+CD62 L+ memory T cells makes a significant difference in pathology and limits tumor growth, while untreated animals have loads of CD44+ T cells in lymphoid organs such as the spleen." (PMID 35444547, 2022). "Overexpression of CD44 in various cancer cells and its affinity for HA suggest a high potential for CD44 as a desirable target for enhancing tumor-selective drug delivery." (PMID 35762636, 2022). "In this review, we describe the glycosylation modification characteristics and the potential of glycosylation alterations as a tumor therapy involving the glycoprotein CD44." (PMID 35936713, 2022). "Univariate analysis demonstrated that tumor diameter (p < 0.001), CD44 (p < 0.001), OTP (p < 0.001), mitotic count (p < 0.001), and Ki-67 (p < 0.001) were significantly associated with distant metastases at follow-up." (PMID 35805004, 2022). "Hyaluronic acid (HA), through its interactions with the cluster of differentiation 44 (CD44), acts as a potent modulator of the tumor microenvironment, creating a wide range of extracellular stimuli for tumor growth, angiogenesis, invasion, and metastasis." (PMID 35456622, 2022). "Inhibition of PDPN-mediated tumor progression by regulating CD44 glycosylation deserves further in-depth research." (PMID 35936713, 2022). "Using flow cytometry, vaccinated mice, both naïve and tumor-bearing, displayed significant increases in the proportion and number of peritoneal effector memory (CD44+CD62L(low)) CD4+ and CD8+ T cells compared to unvaccinated mice (Day 25)." (PMID 36142437, 2022). "Evidence that local administration of IFNα-MSCs contributed to a systemic anti-tumor effect was provided by the increase in CD44+CD62L+ CD8+ T cells in tumor draining lymph node observed in tumors injected with IFNα-MSCs." (PMID 35145233, 2022). "As a result, the supramolecular nanocomplexes showed excellent HA-mediated tumor targeting by recognizing CD44 overexpressed on the surface of tumor cell membranes." (PMID 34987658, 2022). "Of note, TIGIT expression was limited to the CD44+ memory subset and the expression level increased over time during tumor development." (PMID 36569934, 2022). "The adhesion of neoplastic cells becomes more efficient when it has more CD44 protein on their surface, which by binding with hyaluronic acid affects the growth and development of the tumor." (PMID 36012171, 2022). "Whereas nsECT2 and nsECT3-treated mice had higher expression levels of CD44 and GITR on tumour-associated cytotoxic T cells." (PMID 36551739, 2022).
tumor (continued). "Regarding pathological processes in tumors, the binding of HA to CD44 can regulate immune cell recruitment, T cell activation, immune response, and tumor progression." (PMID 35410993, 2022). "The efficacy of liposomes was evaluated through an in vivo bioluminescence assay, in which the Lipo-CD44-TF/GVC group reduced the tumor growth when compared with Lipo-TF/GVC and the control." (PMID 35456655, 2022). "The immunoprecipitation result indicated that extracellular Eno1 interacted with a membrane-bound CD44 in tumor cells and suppressed the progression of tumor cells." (PMID 35547745, 2022). "As already mentioned, it is a ligand of CD44; because it is overexpressed in several types of cancer, it is a potential target to increase the specificity of treatments toward tumor cells." (PMID 36145331, 2022). "By modifying with hyaluronic acid (HA)-conjugated PDA, the resulting nanoplatform were further functionalized to specifically target CD44 overexpressing tumor cells." (PMID 36153522, 2022). "To validate that our CRC metastasis model also resembles the clinical situation in terms of stem cell-like characteristics, we stained primary tumor cells, liver metastases and PC with antibodies against the stem cell markers CD44, CD133, and c-Myc." (PMID 35844581, 2022). "In NIR-PIT targeting CD44 positive oral squamous cell carcinoma and breast cancer in a mouse model, tumor progression was significantly inhibited and survival was prolonged." (PMID 35884975, 2022). "CD44, a cell adhesion receptor, not only plays a key role in tumor cell metastasis, but also has a great impact on regulating epithelial–mesenchymal plasticity and stemness of cancer stem cells." (PMID 36358852, 2022). "Our study evaluated the correlation between MAPK3, CD44, and tumor-infiltrating immune cells in the AML microenvironment by applying the “GSVA” package." (PMID 36612069, 2022). "HA has also demonstrated tumor-targeting ability due to its high affinity for CD44, a family of single-pass transmembrane glycoproteins overexpressed in a variety of cancer cells and recognized as a surface marker for cancer stem cells (CSCs)." (PMID 35456631, 2022). "This was also resonated in clinical studies, wherein molecular profiles of tumours treated with chemotherapy closely resembled the gene profiling of CD44+CD24− cells." (PMID 35159385, 2022). "Then, the immunofluorescence staining of the CD44 in tumor tissues after phosphate-buffered saline (PBS) (control) or HDDA treatment was carried out." (PMID 36319625, 2022). "Osteoclast secretome-derived Hsp90ab1 and Eno1 inhibited tumor progression by suppressing TGF-ß signaling and interacting with CD44, facilitating tumor cell killing by natural killer (NK) cells." (PMID 35994202, 2022). "In the same way, the ΔCD44+CD133+ non-tumor-initiating cell population was also assessed to evaluate if the CD44+CD133+ tumor-initiating Caco-2 cells were eliminated successfully." (PMID 35433695, 2022). "CD44 positive expression was observed in the tumour cores of all patients and in the basal layer, which was expected since most epithelial stem cells are in the basal layer of the oral mucosal lining." (PMID 35296132, 2022). "Correspondingly, the number of the tumor sphere and percentage of CD44+/CD24−/low population were significantly increased in LIN28A knockdown CAL51 cells followed by YAP1 overexpression." (PMID 35102250, 2022). "As is known, the availability of CD44 at the cell surface provides cancer cells with mechanisms of survival that perpetuate tumor growth." (PMID 35328491, 2022). "The population of CD44+ OC cells possess self-renewal, tumor initiating and sphere-forming capacities." (PMID 35269636, 2022). "According to the results, tumor cells overexpressing CDCA8 had the highest proliferation capacity, whereas tumor cells with knockdown of CD44 had the lowest proliferation capacity." (PMID 36358852, 2022).
tumor (continued). "A tumor‐targeting nanomedicine is prepared by encapsulating indocyanine green into CD44 specifically binding material, a hyaluronic acid conjugated lipid poly(ethylene glycol)." (PMID 35470595, 2022). "A recent study shows that disruption of tumor HA synthesis or blocking HA binding to CD44 on TAM effectively increased the proportion of M1-TAMs by upregulating SIRPα." (PMID 36419877, 2022). "Due to the abundant surface markers of CD44 on C6 cells, we expected that the same transcytosis pattern would take place in both 3D tumor spheroids and tumor tissues." (PMID 35458619, 2022). "CD44, which is strongly expressed in stromal cells and weakly expressed in tumor cells, inhibits osteoclast genesis depending on the microenvironment." (PMID 36415832, 2022). "A large number of vesicles were stained by anti-CD44-fluorescein isothiocyanate (FITC) (green) in the tumor slice collected from the HDDA-treated mouse, demonstrating the in situ production of HMVs in the tumor tissues." (PMID 36319625, 2022). "We show that Juglone and KPT6566 suppress proliferation and colony formation of CD44+CD133+ tumor-initiating Caco-2 cells in vitro, and hamper the tumorigenic capacity of CD44+CD133+ tumor-initiating Caco-2 cells in vivo." (PMID 35433695, 2022). "More recently, it has been shown that the transfer of CD44 by tumor-derived extracellular vesicles is a possible gateway for cancer metastasis." (PMID 35359362, 2022). "The possibility of CD44 isoforms switching back and forth has an important implication for understanding the biology of tumor plasticity so as to decisions for the patients’ therapy." (PMID 35931675, 2022). "αPD‐L1 enhances the protein expression of E‐cadherin, and weakens the protein expression of vimentin, VEGF and CD44 in tumour tissues." (PMID 36372977, 2022). "We provide evidence of (p)EMT occurring in virtually all lesions to a various extent, and, importantly, of the presence CD44+ CD271+ tumor cell subsets that likely represent CSCs." (PMID 35215208, 2022). "The formulation of HA-mExo-miR204 can specifically target CD44-positive tumor cells in vitro, with a concomitant increase in miR-204 intracellular uptake and anti-proliferation activity." (PMID 36231028, 2022). "The highly specific binding of CD44 and HA and the favorable biocompatibility of HA are essential for the design and preparation of HA-mediated tumor-targeting drugs." (PMID 35953863, 2022). "Next, we examined the effect of Hermes-1, an anti-CD44 blocking antibody raised from rat, on tumor cell killing by NK cells." (PMID 35436988, 2022). "We have previously reported that the interaction of CD44 with HA activates various oncogenic signaling pathways, leading to tumor cell survival, proliferation, and invasion." (PMID 35164076, 2022). "First, the CD90/CD44 status of these model cells was verified by flow cytometry, as CD44 has been reported to be involved in tumour growth and metastasis in head and neck squamous cell cancer." (PMID 35565415, 2022). "We have previously reported that imaging features of GBM on MRI and Met-PET well correlated with the expression level of CD44 in the tumor tissues of GBM." (PMID 35624954, 2022). "In particular, we discovered that macrophage migration inhibitory factor (MIF), which interacts with CD74+CXCR4+ and CD74+CD44+, was specifically expressed in tumor samples." (PMID 35967424, 2022). "In a tumor sphere formation assay, after inhibiting of exosome derived from G-MDSCs, the tumor sphere numbers, CD44+ cell percentages and CD133+ cell percentages were decreased." (PMID 35154134, 2022). "CD44 is a transmembrane molecule with multiple isoforms that overexpresses in many tumors and promotes tumor formation by interacting with the TME." (PMID 36559056, 2022). "Tumor cells that expressed CD44 on their layers can also be used in the targeting of HA-based formulation." (PMID 35860333, 2022).
tumor (continued). "The worst overall survival was seen in patients whose tumor was CD44-high/IGF1R-high (n = 42, mean survival 22.8 months)." (PMID 35931675, 2022). "Double-positive CD44+/CD117+ cells are highly capable to recapitulate the original tumor after being transplanted into experimental animals." (PMID 36612107, 2022). "CD44 proteins, which form a multifunctional family of single-chain transmembrane glycoproteins, play an essential role in tumor progression and metastasis." (PMID 35898884, 2022). "In our study, CD44 expression was higher in tumor tissue, in agreement with previous published data." (PMID 36291969, 2022). "Much evidence shows that CD44 is a crucial molecule involved in inferior prognosis and tumor metastasis in TNBC cancers." (PMID 35845934, 2022). "Hyaluronic acid functionalized/all-trans-retinoic acid- (ATRA) loaded albumin-based cationic NPs were prepared and evaluated in CD44 overexpressed CSCs in in vivo lung metastasized tumor models." (PMID 35163777, 2022). "The disulphide link is broken in the tumour’s cytoplasmic microenvironment by reduction processes when the micelles penetrate the tumour through the active target, CD44; this results in drug release and tumour growth inhibition." (PMID 36079777, 2022). "In several types of cancers, CD44 was consequently recognized as a cancer stem cell marker that has been indicated to participate in tumour progression, metastasis and drug resistance." (PMID 36376959, 2022). "Further analysis showed that ligand-receptor pairs, including MIF − (CD74 + CXCR4), MIF − (CD74 + CD44), MDK–NCL and LGALS9 − CD45, etc. mediated the communication between m6A associated subtypes of TME cells and tumor epithelial cells." (PMID 35509079, 2022). "It was determined that the pH-sensitive strategy to release the CD44 inhibitor from the nanodevice at the acidic tumor microenviroment enhanced the efficient interaction with the CD44 receptor and significantly reduced HA binding." (PMID 35456622, 2022). "To investigate the relationship between the two HA receptors, we calculated the ratio between the tumor-tissue levels of CD44 and RHAMM." (PMID 35267625, 2022). "The anti-tumorigenic potential of KPT6566 was also analyzed in a clonogenic assay and by growth curve analysis of CD44+CD133+ tumor-initiating Caco-2 cells." (PMID 35433695, 2022). "Combination treatment with both agents together further suppressed tumor volume and resulted in greater inhibition of CD44+/CD24− CSCs per tumor volume compared to single treatment with docetaxel or nPKC-θi2." (PMID 35326747, 2022). "Only MMP-2 expression was positively correlated with patient age (τ = 0.31, p < 0.05, Kendall’s rank coefficient), while only CD44 expression was positively correlated with T (tumor) stage (τ = 0.26, p < 0.05, Kendall’s rank coefficient)." (PMID 36079127, 2022). "In summary, our study demonstrates that CD44 is an important factor in the cross-talk between tumor and host cells." (PMID 35992852, 2022). "The CD44+/CD133+ CAL 27 stem-like cells in vivo models revealed that DHEA treatment reduced the HNC stem-like cells’ tumor formation frequency more than control." (PMID 35912234, 2022). "Of note, circulating tumor cells (CTCs) expressing CD44 isolated from patients have been shown to exhibit chemoresistance and multipotency ex vivo." (PMID 35326607, 2022). "At the same time, HA has high affinity with for the CD44 receptor on the cell membrane surface, and the expression of the CD44 protein in tumor cells is abnormally increased compared with that in normal human cells." (PMID 35261298, 2022). "The IHC results showed that CD44 expression in the main tumor body was significantly higher than that in the tumor buds (65.5% vs. 16.1%)." (PMID 35860042, 2022). "Another inhibitor of the TGF-β receptor I, LY2109761, was shown to reduce expression of the CD44 stem cell marker in GSCs and reduce tumor growth and recurrence in an in vivo mouse model." (PMID 35954407, 2022).
tumor (continued). "The survival result showed the worse prognosis of patients with dual high expression of SPP1 and CD44, indicating the pro-tumor role of the SPP1/CD44 axis in the progress of HCC." (PMID 35958556, 2022). "To measure the mitochondrial activity in CD44+CD36+ tumour cells, we first sorted cancer cells for high (H) or low (L) expression of CD44 and CD36, and then quantified the MMP in the different subpopulations." (PMID 35768510, 2022). "The frequencies of both OVA‐specific CD4+ and CD8+ CD44+ effector and CD44+ CD62L+ memory T cells normalized per gram of tumor weight in the SVF SPH+amDC‐transplanted group were significantly higher than those in control groups." (PMID 36058002, 2022). "Increasing some specific forms of CD44 fucosylation in tumors is also thought to promote tumor progression." (PMID 35936713, 2022). "CD44 is a complex transmembrane adhesion glycoprotein, and the adhesion between tumor cells and the host cell’s matrix promotes invasion and metastasis." (PMID 35752750, 2022). "Several experiments demonstrated that CD44+ bladder cells are 10–200 times more likely to give rise to tumor than CD44− cells in immunodeficient mice, demonstrating their high tumorigenicity." (PMID 35903544, 2022). "Hyaluronic acid, a major component of the extracellular matrix, can bind CD44, which belongs to the cell adhesion molecule family and is highly expressed in a variety of tumor cells; therefore, it is often used as a targeting agent." (PMID 35456552, 2022). "Double positive CD44+/CD117+ cells are highly capable to recapitulate the original tumor after being transplanted into experimental animals, and are the main component of sphere-forming cells in ascites." (PMID 35269636, 2022). "The exact mechanisms of the homeobox protein family member contributing to aggressive tumor behavior and the molecular interactions with CD44 remain to be elucidated." (PMID 35805004, 2022). "It is known the intercellular homo-interaction of the ETD happens to drive tumor clusters, while the intracellular CD44 dimerization is mainly dependent on the transmembrane domain (TMD) and CTD where the sequence is highly conserved." (PMID 35733341, 2022). "Another group demonstrated that blocking or silencing Stat3 increased the sensitivity to anoikis in NPC cells, besides that knockdown Stat3 also reserved tumor invasive properties and inhibited expression of CD44." (PMID 36678534, 2022). "Long-lived CD44+ tumour-initiating cells can selectively evade host immune responses and provide a rationale for targeting the PD-1 pathway in the adjuvant therapy setting of SCCHN." (PMID 36316684, 2022). "The novelty of our study consists of the simultaneous assessment of the CD133, CD166, and CD44 gene expression patterns in both tumor and normal samples of CRC patients, obtained through minimally invasive colonoscopy procedures." (PMID 36291969, 2022). "Mounting evidence has demonstrated that CD44 is a critical regulator for self‐renewal, tumour initiation and metastasis in cancer stem cells." (PMID 35908276, 2022). "Activated platelet membrane nanovesicles, which retain almost all of the platelet-proteins, target tumor tissues through P-selectin and CD44, and mediate neutrophil recruitment through P-selectin, ICAM-2, and CCL5." (PMID 36034656, 2022). "Comparing MDA-MB-231, Hs578T and EGF-treated MDA-MB-468 cells silenced for CD44 in vitro, we observed a clear diminution of human tumor cell content in lungs 24 h after injection." (PMID 35805061, 2022). "In the tumor microenvironment, tumor-derived OPN binds to CD44 on activated T cells, thus apparently suppressing T-cell activation." (PMID 36466909, 2022). "We further used Dunn’s test which revealed the significance of KRAS, MMP7, and CD44 expressions in promoting CRC tumor metastasis." (PMID 35203586, 2022). "After adjusting for tumour purity, there was a correlation between CD44 outside CD8B and NOS2 and most of the immune markers." (PMID 36316684, 2022).